CHL1 (cell adhesion molecule L1 like)
Diseases named in the same sentence as CHL1 in open-access papers (continued):
Sharing a sentence is not in itself a finding about the gene and the disease.
colitis (1 paper, 2020). Inflammation of the colon. "CHL1 deficiency exacerbated the development of DSS-induced colitis with pronounced colitis features, including an increase in proinflammatory cytokines and the leakage of FITC from the colon to the serum." (PMID 33240104, 2020). "The changes in the relative intensity of FITC suggest that CHL1 deficiency impaired intestinal barrier function in colitis mice." (PMID 33240104, 2020). "We previously found that the loss of CHL1 exacerbated the dextran sulfate sodium (DSS)-induced colitis in mice." (PMID 33240104, 2020). "CHL1 deficiency induced more pronounced colitis features, exacerbated inflammation, and damage to colonic tissues in DSS-induced mice." (PMID 33240104, 2020). "In the present study, during initial DSS administration, intestinal epithelial functions were impaired and substantially preceded the development of colitis in CHL1-deficient mice." (PMID 33240104, 2020). "Therefore, the precise mechanism by which CHL1 deficiency regulates inflammation during colitis needs to be addressed in the future." (PMID 33240104, 2020). "Accordingly, we speculate that deficiency of CHL1 exacerbates the development of colitis." (PMID 33240104, 2020). "Previous research of our group showed that CHL1−/− mice had more severe colitis features, such as weight losing, fecal blood, and shortening of colon length, but its mechanism and pathological effects were unclear." (PMID 33240104, 2020). "We then detected the expression level of CHL1 protein in colon tissue in response to DSS-induced colitis by western blot assays." (PMID 33240104, 2020). "The data showed that CHL1 expression was increased in the distal colon in a time-dependent manner in DSS-induced colitis." (PMID 33240104, 2020). "Under the same DSS treatment, the severity of colitis was different in CHL1−/− mice, and the numbers of infiltrated neutrophils in the colon tissues were variable." (PMID 33240104, 2020). "Combined the previous results about the function of CHL1, the recent publication of a paper found that CHL1-deficient reduces the inflammatory response in 4% DSS-induced mice colitis, by regulating the balance of Th17/Treg in mice with colitis." (PMID 33240104, 2020). "Here, we investigated the effects of CHL1 on the development of dextran sulfate sodium (DSS)-induced colitis." (PMID 33240104, 2020). "Macrophage infiltration in CHL1−/− mice was significantly higher than that in CHL1+/+ mice in the presence of DSS-induced colitis." (PMID 33240104, 2020). "The previous results showed that CHL1−/− mice had more severe colitis and more significant phenotypes than CHL1+/− and CHL1+/+mice." (PMID 33240104, 2020). "In the present study, we further addressed the role of CHL1 in mouse model of DSS-induced colitis and its’ potential mechanism." (PMID 33240104, 2020). "In the present study, CHL1 may plays an anti-inflammation role initially in DSS-induced colitis, the increased of CHL1 attempts to reduce inflammation in WT mice colon." (PMID 33240104, 2020). "In the present study, it is possible that CHL1 may play an anti-inflammation role in DSS-induced colitis." (PMID 33240104, 2020). "However, the current results cannot exclude this possibility that CHL1 have dual roles by mediating colitis in different DSS doses." (PMID 33240104, 2020). "Therefore, in our preliminary experiment, 2.5% DSS had been used to induce colitis, but the CHL1−/− mice were unable to tolerate and nearly half of the mice died on the 6th day." (PMID 33240104, 2020). "Importantly, HE staining revealed more severe colitis symptoms in DSS-induced CHL1+/− mice than in DSS-induced CHL1+/+ mice." (PMID 33240104, 2020). "We examined whether the change in CHL1 expression affected colonic inflammation and found that CHL1 expression was increased in a time-dependent manner during the development of DSS-induced colitis." (PMID 33240104, 2020). "This study provides a novel functional role of CHL1 in regulating colitis." (PMID 33240104, 2020).
colitis (continued). "This work demonstrated that CHL1 deficiency exacerbated the occurrence and development of DSS-induced colitis with pronounced colitis features, including impaired epithelial barrier function and enhanced inflammation and damage to colonic tissues in mice with DSS-induced colitis." (PMID 33240104, 2020). "Here, we provide new information regarding the impact of CHL1 on DSS-induced colitis." (PMID 33240104, 2020). "To study the correlation between CHL1 and colitis, we used CHL1+/+, CHL1+/−, and CHL1−/− mice in a DSS-induced colitis mouse model." (PMID 33240104, 2020). "Colon tissues were collected from CHL1+/+, CHL1+/−, and CHL1−/− mice after DSS induction to investigate the effects of CHL1 on the development of colitis." (PMID 33240104, 2020). "Thus, the increased expression of CHL1 is involved in anti-inflammation in DSS-induced colitis for WT mice, while this ability of reduce colitis has been lost in CHL1−/− mice." (PMID 33240104, 2020).
COVID-19 (1 paper, 2025). A disease caused by infection with severe acute respiratory syndrome coronavirus 2. "It is not inconceivable that, subsequent to SARS-CoV-2 infection, autoantibodies against the DAAM2 or CHL1 proteins can be produced that may contribute to the neurological manifestations of COVID-19." (PMID 41009363, 2025).
cutaneous melanoma (1 paper, 2013). A primary melanoma arising from atypical melanocytes in the skin. "As EWSR1 gene fusions had not previously been described in cutaneous melanoma, we prioritized CHL-1 and SH4 for further evaluation." (PMID 23637631, 2013).
diabetic retinopathy (1 paper, 2008). "To examine the upregulation of CHL-1 along with genes known to be upregulated in diabetic retinopathy, we performed real-time quantitative PCR." (PMID 18587495, 2008). "CHL-1 (upregulated gene number 20) is a novel gene not previously associated with diabetic retinopathy." (PMID 18587495, 2008).
endometrial cancer (1 paper, 2025). Primary or metastatic malignant neoplasm involving the endometrium (mucous membrane that lines the endometrial cavity). "Similarly, increases in CHL1 gene expression reported in endometrial cancer are driven by lncRNA CHL1-AS1, which sponges miR-6076 to promote cell proliferative and migration." (PMID 40457415, 2025).
esophageal cancer (1 paper, 2020). A primary or metastatic malignant neoplasm involving the esophagus. "In accordance with this hypothesis, an association of decreased CHL1 expression with distant and lymph node metastases, as well as with reduced overall survival was reported for esophageal cancers." (PMID 32284790, 2020).
learning disabilities (1 paper, 2011). "In conclusion, this familial case, characterized by a transmitted 3p deletion containing only the CHL1 gene and associated with a strong phenotypic variability, confirms the hypothesis that the association of terminal 3p deletion, mental retardation and learning disabilities is not casual." (PMID 21457564, 2011).
liver cancer (1 paper, 2023). An epithelial or non-epithelial malignant neoplasm that arises from the liver.
lung squamous cell carcinoma (1 paper, 2011). "There was a higher frequency of CHL1 mRNA decrease in lung squamous cell carcinoma compared to adenocarcinoma (81% vs. 38%, P = 0.02) without association with tumor progression." (PMID 21408220, 2011).
lymph node metastasis (1 paper, 2025). "Reduced CHL1 expression is associated with poor differentiation, increased invasion, lymph node metastasis, advanced tumor stage, and decreased overall survival." (PMID 41374320, 2025).
mastitis (1 paper, 2023). Inflammation of breast tissue during lactation or postpartum due to an obstructed duct or infection. "The greatest potential levels of mRNA were found for the mastitis-affected dairy cows’ NFkB (2.63 ± 0.11) and COX18 (2.64 ± 0.16) genes, respectively, while CHL1 (0.44 ± 0.12 and 0.64 ± 0.11) had the lowest levels in both Holstein and Montbéliarde dairy cows." (PMID 36669036, 2023).
mood disorder (1 paper, 2017). A cognitive disorder a disturbance in which the person's mood is hypothesized to be the main underlying feature. "Moreover, CHL1 expression was downregulated in the hippocampus of mice exposed to early post-natal stress, a known aggravator of mood disorders." (PMID 29163031, 2017).
Neurodevelopmental delay (1 paper, 2015). "Furthermore, in humans deletions of CHL1 have been described in patients with neurodevelopmental delay characterized by learning and language difficulties, seizures." (PMID 26279679, 2015).
neuropathic pain (1 paper, 2022). Chronic pain caused by damage to nerve fibers. "Synaptic proteins such as gelsolin, apolipoprotein C1, apolipoprotein E, contactin-1, and neural cell adhesion molecule L1-like protein were altered in cerebrospinal fluid of neuropathic pain patients and contributed to pain treatment." (PMID 36545122, 2022).
oral cancer (1 paper, 2017). "The rationale of choosing these CNA associated genes was basically due to LRP12, TPM2, EGFR, CCND1 being matched with ICGC and TCGA databases whereas FSCN1, CLPTM1L, CHL1 and CSMD1 had been found to be associated with oral cancer." (PMID 28384287, 2017).
schwannoma (1 paper, 2016). A benign, usually encapsulated slow growing tumor composed of Schwann cells. "CHL1 encodes a neural cell adhesion factor and has been identified in a microarray expression analysis as a considerably upregulated gene in schwannomas compared to control nerve cell samples." (PMID 27096627, 2016).
spinal cord injury (1 paper, 2022). Penetrating and non-penetrating injuries to the spinal cord resulting from traumatic external forces (e.g., WOUNDS, GUNSHOT; WHIPLASH INJURIES; etc.). "We had found that young adult female mice deficient in CHL1 recovered better than their wild-type female littermates after thoracic Spinal Cord Injury (SCI)." (PMID 36411762, 2022).
stomach cancer (1 paper, 2011). "In stomach cancer a statistically significant change of CHL1 expression (both up- and down-regulation) was shown in the group with metastases relative to the group without metastases (88% vs. 45%, P = 0.02)." (PMID 21408220, 2011).
xeroderma pigmentosum group D (1 paper, 2017). Any xeroderma pigmentosum in which the cause of the disease is a mutation in the ERCC2 gene. "DinGEc is a structure-specific enzyme, related to human xeroderma pigmentosum group D (XPD), FANCJ, also known as BACH1, as well as to Saccharomyces cerevisiae Rad3 and Chl1, and Schizosaccharomyces pombe Rad15." (PMID 29121674, 2017).
tumor (89 papers, 1996 to 2026). "It has been proposed that alterations in genes involved in neurite maturation, such as CHL1, can trigger NB itself, inducing high-risk tumor features." (PMID 33326488, 2020). "We previously demonstrated that CHL1 acts as a tumor suppressor gene in NB and that its over-expression causes cell differentiation and clearly reduces proliferation and tumor growth in a preclinical mouse model." (PMID 33326488, 2020). "Reduced CHL1 tissue expression was associated with advanced tumor stages and a localization distant from the stomach indicating a worse tumor biology." (PMID 32284790, 2020). "Further studies are needed to unveil the fine mechanisms underlying CHL1-mediated tumor suppression." (PMID 29899830, 2018). "Down-regulating CHL1 expression results in increased proliferation and invasion, and CHL1 deficiency also promotes tumor formation in vivo." (PMID 29089868, 2017). "CHL1 deficiency promotes tumor formation in vivo, and CHL1 is downregulated in human BC." (PMID 32775417, 2020). "Hence, reduced membranous CHL1 expression is associated with advanced tumor stages and unfavorable localizations of GIST." (PMID 32284790, 2020). "CHL1 may function like haploinsufficient tumor-suppressor genes, where a partial loss of CHL1 may be sufficient to result in a cellular phenotype that leads to NB tumorigenesis." (PMID 29899830, 2018). "Thus, the bad prognostic effect of increased serum CHL1 caused by increased local CHL1 cleavage might lead to a loosening of cell adhesions within the GIST intensifying the spread of tumor cells and thereby inducing earlier recurrences." (PMID 32284790, 2020). "RNA sequencing results revealed significant differences in gene expression, with key genes (upregulated CXCR4, OPCML, and S100A2, and downregulated ATP1A3, CHL1, HLA-DRA, and IL-1β) associated with tumor invasiveness." (PMID 41374320, 2025). "After transfection, overexpression of CHL1 inhibited tumor cell growth while the knock-down group exhibited accelerated cell viability and a faster cell growth trend compared to the control group." (PMID 35433461, 2022). "CHL1 is a close homolog of L1, a cell adhesion molecule that plays major roles in neural and tumor cell functions." (PMID 36411762, 2022). "Altogether, these results highlighted the pivotal role of PTPRG and CHL1 in tumor growth and progression of ccRCC." (PMID 35433461, 2022). "Exosomal miR-338-3p suppresses tumor cells' metastasis by downregulating the expression of CHL1 through MAPK signaling pathway inactivation." (PMID 34718336, 2021). "Upregulated CHL1 expression enhanced NSCLC cells’ progression by promoting tumor cells proliferation while suppressing their apoptosis." (PMID 34718336, 2021). "In order to elucidate the effects of miR-338-3p/ CHL1 on tumor cells, we conducted rescue experiments." (PMID 34718336, 2021). "Next, to explore the function of CHL1 in tumor cells, we knocked down CHL1 expression in A549 cells and SK-MES-1 cells." (PMID 34718336, 2021). "The rescue experiments demonstrated that the effect of suppressed miR-338-3p levels on tumor cells proliferation and apoptosis was rescued by inhibited CHL1 levels." (PMID 34718336, 2021). "Consulting public NB patients’ datasets, we remarked that high CHL1 expression was related to better outcomes and higher survival rates, considering tumor stage, age at diagnosis, and MYCN oncogene amplification." (PMID 33326488, 2020). "In NB patient cohorts separated by tumor stage from two different datasets, we found that a more expressed CHL1 gene correlated with better event-free survival rates in patients with both low stage (1, 2, 3, 4S) and high stage disease." (PMID 33326488, 2020). "To gain insight into the molecular mechanisms underlying the apparent increased aggressiveness of CHL1 TPC2 KO cells, we investigated the potential links with an important emerging pathway associated with tumour initiation and progression." (PMID 32846966, 2020).
tumor (continued). "Here we provide evidence that CHL1 firmly interacts with ezrin in NB cells, and that this interaction leads to a higher neuronal differentiation degree and, consequently, to a lower tumor invasiveness potential." (PMID 33326488, 2020). "Recently, promoter hypermethylation of CHL1 and RHCG, two novel tumor suppressor candidates, has been reported to be associated with poor differentiation and increased invasion of ESCC, as well as advanced tumor stage and decreased overall survival." (PMID 33194605, 2020). "Seven cases presented cnLOH (four TNBC), and six (one TNBC) had losses covering CHL1, a putative tumor suppressor gene." (PMID 33007869, 2020). "In conclusion, our data identified ezrin as a determining effector molecule that cooperates with the NB tumor suppressor CHL1 in inducing neuronal differentiation and lower tumor aggressiveness." (PMID 33326488, 2020). "In this study, the expression status of CHL1, its potential tumor suppressive role and molecular mechanism in NPC development were characterized." (PMID 31523184, 2019). "Collectively, the results of our findings indicated that CHL1 exerts the tumor-suppressive function in NPCs by regulating the Akt signaling pathway." (PMID 31523184, 2019). "Molecular analysis revealed that the tumor-suppressive effect of CHL1 regulates cell cycle arrest at G1/S checkpoint by down-regulating cyclin D1, which is accumulating before S-phase and reaching its maximum." (PMID 31523184, 2019). "Each CHL1 positive tumor was classified Hughes grade 1, which differed significantly from CHL1 negative samples (p=0.01)." (PMID 31989042, 2019). "In this study, a resident tumor suppressor gene CHL1, located on human chromosome 3p26.1, was reported to show tumor suppressive function in NPC." (PMID 31523184, 2019). "In the paired tumor and non-tumor tissue, down-regulation of CHL1 was detected in 12/15 (80.0%) of the NPC cases." (PMID 31523184, 2019). "That parallels our findings of positive protein expression of CHL1 in low tumor grades Hughes 1a/b by immunohistochemistry only." (PMID 31989042, 2019). "The expression of miR-21-5p was also down-regulated by miR-21-5p inhibitor in vivo (P < 0.01).Therefore, miR-21-5p promoted the tumor growth by inhibiting CHL1 expression in vivo as well." (PMID 30134821, 2018). "The result of in vivo experiment indicated that inhibition of miR-21-5p suppressed COAD tumor growth and knockdown of CHL1 promoted the growth of COAD tumors." (PMID 30134821, 2018). "In the meantime, we explored in vivo experiment which confirmed that miR-21-5p promoted the tumor growth by inhibiting CHL1 expression." (PMID 30134821, 2018). "Consistent with our in vitro findings, these observations support the conclusion that CHL1 acts as a tumor suppressor in NB." (PMID 29899830, 2018). "Previous study verified that CHL1 gene was one of the putative tumor suppressor genes localized on human chromosome 3." (PMID 30134821, 2018). "In this study, we provided evidence of the tumor suppressive effect and prognostic potential of CHL1 in NB." (PMID 29899830, 2018). "These regions harbour the tumour-suppressor gene known as Cell Adhesion Molecule L1 (CHL1), which has been recently shown to contribute in oral tumourigenesis." (PMID 28384287, 2017). "The final tumor volume in mice treated with siRNA targeting CHL1 was lower than that in mice treated with control siRNA, although no statistical significance was detected (1689.41 ± 239.46 vs. 1877.50 ± 325.11 mm3, p = 0.2768 vs. control siRNA)." (PMID 29089868, 2017). "H&E staining and immunohistochemical staining were performed to analyze changes in the xenograft tumor in response to CHL1 down-regulation." (PMID 29089868, 2017). "CHL1 gene – close homolog of L1, also known as CALL - cell adhesion L1-like encodes a one-pass trans-membrane cell adhesion molecule (CAM) capable of both homotypic and heterotypic binding and has tumor suppressing properties." (PMID 23773282, 2013).